HLTF (helicase like transcription factor)
Diseases named in the same sentence as HLTF in open-access papers (continued):
Sharing a sentence is not in itself a finding about the gene and the disease.
thyroid (1 paper, 2014). "Moreover, our in vivo study revealed that the expression of one or more truncated HLTF protein variants (HLTFMet1ΔA and HLTFMet1ΔB) was associated with thyroid tumorigenesis." (PMID 25005870, 2014). "This study reveals an association between HLTF expression level and thyroid neoplastic progression." (PMID 25005870, 2014). "This study demonstrates a correlation between HLTF expression level and thyroid neoplastic progression." (PMID 25005870, 2014). "The presence of HLTF was investigated using quantitative and semi-quantitative immunohistochemistry in a series of 149 thyroid lesion specimens." (PMID 25005870, 2014).
thyroid tumor (1 paper, 2014). A benign or malignant neoplasm affecting the thyroid gland. "The first aim of our study was to quantitatively investigate HLTF expression in a series of 80 thyroid tumors." (PMID 25005870, 2014). "Nuclear HLTF immunostaining may therefore represent a new marker in thyroid tumors that could be used with FNA in an attempt to better distinguish benign thyroid nodules from malignant tumors." (PMID 25005870, 2014). "The decrease in HLTF staining was statistically significant during thyroid tumor progression in terms of both MOD, which corresponds to the mean staining intensity (Kruskall-Wallis: p < 0.0005), and the LI, which corresponds to the percentage of immunopositive cells (Kruskall-Wallis: p < 10−6)." (PMID 25005870, 2014).
tumor (38 papers, 2006 to 2025). "Previous studies have shown the progressive loss of HLTF from tumor cells correlates with negligible HLTF expression in the TME." (PMID 34010296, 2021). "Human HLTF, implicated in error-free replication of damaged DNA and tumour suppression, exhibits a HIRAN domain, a RING domain, and a SWI/SNF domain facilitating DNA-binding, PCNA-polyubiquitin-ligase, and dsDNA-translocase activities, respectively." (PMID 26350214, 2015). "Previous studies revealed that HLTF is frequently inactivated in many tumours, indicating that loss of HLTF function promotes carcinogenesis." (PMID 26350214, 2015). "In conclusion, our data suggest that HLTF gene activation is linked to initial steps of carcinogenesis in this model and should be investigated in early stages of other neoplasms." (PMID 16762066, 2006). "Progressive loss of HLTF expression from tumor cells correlates with tumor staging." (PMID 34010296, 2021). "Moreover, H. Ding’s group confirmed a tumor suppressor function by mouse transgenesis: HLTF deficiency in Apc−/+ mice induced the transition from colon adenoma to carcinoma with high chromosomal instability." (PMID 25005870, 2014). "explores how the loss of Helicase-like transcription factor (HLTF), a tumor suppressor, leads to metabolic reprogramming within specific regions of the TME, particularly in lymphatic intravascular metastatic niches." (PMID 39711954, 2024). "HLTF has been identified as a tumor suppressive biomarker that is methylated in non-small cell lung cancer and hypermethylation of HTLF is associated with poor survival." (PMID 36670110, 2023). "We found that high HLTF expression in HCC was positively related to tumor diameter, TNM stage and vascular invasion." (PMID 36670110, 2023). "The results revealed that compared with that in normal liver tissues, HLTF expression was significantly increased in tumor tissues, and HLTF expression was significantly correlated with clinicopathological characteristics and patient outcome." (PMID 36670110, 2023). "Hypermethylated HLTF DNA in serum samples significantly correlated with tumor size, more aggressive tumors, advanced stage (III or IV) metastatic disease, including micro-metastasis, and shorter survival." (PMID 37682902, 2023). "Treatment with DNA methylation inhibitors can restore the activity of the HLTF gene and slow the rate of tumor progression." (PMID 36670110, 2023). "Nevertheless, in the experimental model of estrogen-induced renal carcinogenesis, HLTF expression was detected at the early stage of tumor progression, indicating that the activation of the HLTF gene is related to the initial steps of carcinogenesis." (PMID 36670110, 2023). "HLTF plays a tumor-promoting role by activating the ERK/MAPK signaling pathway by increasing SRSF1 protein stability." (PMID 36670110, 2023). "Epigenetic silencing of HLTF in tumor cells has long been the experimental focus to the exclusion of HLTF in the TME." (PMID 34010296, 2021). "The HCT116 human colon carcinoma cell line was selected because it expresses HLTF, displays leading edge invasion in xenograft tumor model, and recapitulates the multi-step dissemination process to the liver and lungs." (PMID 34010296, 2021). "Hltf-deletion from the TME played a major role in the pathogenesis of inflammation and linked protein S-nitrosylation in primary CDX tumors with spatiotemporal continuity in metastatic progression when the tumor cells expressed HLTF." (PMID 34010296, 2021). "Progressive epigenetic silencing of HLTF in tumor cells is accompanied by negligible expression in the tumor microenvironment (TME)." (PMID 34010296, 2021). "Promoter methylation of three genes (HPP1, HLTF, and hMLH1) in blood cfDNA was positively correlated with tumor size." (PMID 33693004, 2021). "Helicase-like transcription factor (HLTF) HLTF is the human ortholog of yeast Rad5 and has roles in transcription, chromatin remodeling, DNA damage repair, and tumor suppression." (PMID 31652959, 2019).
tumor (continued). "The Helicase-like Transcription Factor (HLTF) is a tumor suppressor, altered in cancer either by gene hypermethylation or mRNA alternative splicing." (PMID 29661164, 2018). "HLTF promoter hypermethylation in the blood of cancer patients has been investigated as a tumor biomarker to predict prognosis and survival." (PMID 29807746, 2018). "Overall, the level of HLTF expression was lower in tumours from patients than in cell lines (WT HLTF: 20.6 vs. 71.5, p = 9.3 × 10− 11 and I21R HLTF: 2.2 vs. 18.3, p = 2.8 × 10− 12, Wilcoxon rank-sum test)." (PMID 29661164, 2018). "HLTF expression was assessed by RT-ddPCR in 171 tumours from patients with surgically resected stage I-II NSCLC." (PMID 29661164, 2018). "This research found HLTF methylation to be significantly higher in patients that experienced tumour recurrence (p = 0.014)." (PMID 29038612, 2017). "Methylation of HLTF was reported to strongly correlate with tumor size, metastatic disease, and tumor stage; furthermore, it was associated with disease recurrence." (PMID 29147109, 2017). "HLTF has furthermore been suggested as a potential tumour suppressor gene, as it was found to be silenced in various cancer types and associated with the first stages of carcinogenesis." (PMID 24198246, 2014). "While methylation of HLTF was only correlated with metastastatic disease, methylation of HPP1 was also associated with local tumor extent and nodal status as well as tumor grade with high statistic significance." (PMID 24708595, 2014). "HLTF is a tumor suppressor silenced by promoter hypermethylation in gastrointestinal tract and select uterine cancers." (PMID 23826137, 2013). "Although every cell stained for HLTF at this early stage, the number of HLTF-positive cells decreased to 10% with cancer progression, and these positive cells were dispersed in the tumor mass." (PMID 16762066, 2006). "The HLTF RING domain is highly similar to the RING domain of BRCA1, a tumor suppressor gene mutated in breast and ovarian cancer." (PMID 16762066, 2006). "We observed a rarefaction and a scattered distribution of HLTF positive cells during tumor progression." (PMID 16762066, 2006). "A strong labeling was already detected in small tumor buds, making HLTF an early cancer marker in this model." (PMID 16762066, 2006). "Radiation‐induced lipid peroxidation and chemotherapy‐triggered ROS accumulation could be amplified by HLTF inhibition, leading to ferroptosis‐dependent tumour cell death." (PMID 40000422, 2025). "HLTF can also be used as an independent prognostic marker of tumor recurrence." (PMID 38163902, 2024). "HLTF-deleted cancer cells recovered from DNA damage at a transcriptomic level induction of DNA repair and OXPHOS genes linked to an amoeboid-associated phenotype at the tumor border (confocal microscopy)." (PMID 37682902, 2023). "The results indicated that HLTF expression was upregulated in HCC tumor tissues." (PMID 36670110, 2023). "HLTF is a putative tumor suppressor because of its role in DNA damage tolerance mechanisms." (PMID 34010296, 2021). "As in NSCLC cell lines, the level of WT HLTF expression was significantly higher than the level of I21R HLTF expression in tumours of patients with NSCLC when considering all patients (median 20.6 vs. 2.2 respectively, Wilcoxon signed-rank test, p = 2.2 × 10− 16)." (PMID 29661164, 2018). "A large body of evidence indicates that HLTF is a tumor-suppressor gene." (PMID 29807746, 2018). "HLTF is a tumor suppressor silenced by promoter hypermethylation." (PMID 29975766, 2018). "Although the reason for epigenetic HLTF silencing is unknown, it is assumed the elimination of HLTF’s DNA damage repair function benefits tumor progression." (PMID 29975766, 2018).
tumor (continued). "The tumor suppressor role of CHFR was suggested to be a consequence of its ability to cause degradation of HLTF and protect against HLTF-mediated cell migration by modulating HLTF’s regulation of expression of plasminogen activator inhibitor-1 (PAI-1) implicated in tumor invasion and metastasis." (PMID 25906194, 2015). "In concert with its potential tumour suppressor function, experiments performed by our group and others defined HLTF as a replication stress response protein that specifically acts during the replication of damaged DNA and contributes to error-free damage tolerance." (PMID 26350214, 2015). "In addition, the percentage of HLTF positive nuclei differed significantly among the 4 tumor groups (Kruskal-Wallis p < 10−6)." (PMID 25005870, 2014). "Moreover, three truncated HLTF forms (95-kDa, 80-kDa and 70-kDa) were also found in these tumor cells." (PMID 25005870, 2014). "HLTF participates in transcription, chromatin remodeling, DNA damage repair, and tumor suppression." (PMID 23826137, 2013). "This suggests that HLTF expression persists for many generations in subpopulations of tumor cells." (PMID 16762066, 2006). "This hypothesis will have to be evaluated by analyses of HLTF expression in clinical samples of early primary tumours." (PMID 16762066, 2006). "In contrast, a 20-fold increase in mouse HLTF/Zbu1 mRNA concentration has been observed in several established cell lines of tumor origin (HeLa, MCF7...,) suggesting that HLTF over-expression could be associated with neoplastic transformation." (PMID 16762066, 2006). "HLTF expression either occurred in scattered cells, or was seen in tumor cell groups." (PMID 16762066, 2006). "However, other evidences indicated a 20-fold HLTF overexpression in cell lines derived from various neoplasms (ovary, breast, cervix, kidney..)." (PMID 16762066, 2006). "This restricted period of expression associated with an asynchronous development of tumoral foci might explain why only 10% of tumor cells exhibit HLTF overexpression." (PMID 16762066, 2006). "HLTF could be used as an independent prognostic marker of tumor recurrence." (PMID 36670110, 2023). "As detailed in a review article we published recently, the HLTF gene could be involved in various ways during the stages of tumour initiation and progression, by its ability to alternatively express proteins of different sizes with distinct functions ranging from tumour suppressor to oncoprotein." (PMID 29661164, 2018). "Therefore, the detection of methylation in the genes SST, TAC1, SEPT9, and HLTF may enable early detection and assist in more effective intervention during postresection tumour recurrence compared to conventional markers." (PMID 29038612, 2017). "However, the exact mechanisms leading to the release of the tumor markers discussed here with prognostic (HLTF and HPP1) or diagnostic (NEUROG1) information have not been examined so far." (PMID 24708595, 2014). "The results revealed that HLTF mRNA levels were higher in GBM tissues than in non‐tumour tissues, and tissues with elevated LINC01088 levels exhibited upregulated HLTF protein expression." (PMID 40000422, 2025). "Helicase-like transcription factor (HLTF), which belongs to the SWI/SNF family, participates in tumor progression in two ways: epigenetic silencing by DNA methylation, or overexpression." (PMID 38163902, 2024). "Helicase-like transcription factor (HLTF), belonging to the SWI/SNF family, is involved in tumor progression in two ways, either epigenetic silencing by DNA methylation or overexpression." (PMID 36670110, 2023). "The shift in the global focus from ‘only’ tumor cells to mechanisms shared by tumor cells and cells of the tumor microenvironment (TME) showed negligible HLTF protein in fibroblasts and endothelial cells of the TME." (PMID 37682902, 2023).
tumor (continued). "Further experiments confirmed that HLTF affected the levels of p-ERK in HCC cells; after transfected HLTF cells were treated with SCH772984, ERK/MAPK pathway activation and the tumor-promoting effects mediated by HLTF were suppressed." (PMID 36670110, 2023). "HLTF, ITGA10, PLCG1, and TTC3 are potential tumor antigens of STS for the development of mRNA vaccines." (PMID 35053609, 2022). "HLTF belongs to the SWI/SNF family of proteins involved in chromatin remodeling and DNA repair, suggesting that it acts as a tumor suppressor gene." (PMID 35154316, 2022). "Based on the results for both SEPT9 and HLTF genes in blood samples we found that the expression of these two genes in tumor samples was lower than normal and the reduction of expression for SEPT9 gene was more than the HLTF gene." (PMID 33936232, 2021). "The researchers then examined the prognostic values of serum HLTF and HPP1 methylation in subgroup analyses according to tumor stage." (PMID 28187169, 2017). "The balancing act between HLTF and SHPRH is likely to play a paramount role in their tumor suppressor functions as they operate to suppress mutagenesis in a damage-specific manner." (PMID 25906194, 2015). "Promoter CpG methylation of HLTF and HPP1/TPEF were found to be correlated with tumour size, metastatic disease and tumour stage with multivariate analysis indicating strong association with poor outcome." (PMID 25622259, 2015). "The fact that necrosis tends to be found more often in larger, more aggressive tumours and advanced cancer stages, which was likewise the case for LDH as well as methylated HLTF and HPP1 in our data, also suggests an interrelation." (PMID 24708595, 2014). "Genetic evidence indicates a major role for yeast Rad5 in template switch and that both Rad5 and its human orthologue, Helicase-like transcription factor (HLTF), a potential tumour suppressor can facilitate replication fork reversal." (PMID 24198246, 2014). "NAV3 is a helicase and it was recently shown that a similar gene, the helicase-like transcription factor (HLTF), can have a dual-type of activity, behaving both as an oncogene and as a tumour suppressor." (PMID 22173670, 2012). "HLTF, BNIP3, H2AFX, CACNA1G, TGIF, ID4 and CACNA1A were identified as novel tumor suppressor candidates methylated in lung tumors." (PMID 20849603, 2010). "However, in a few tumor samples that were fixed in paraformaldehyde we could detect the same proportion of HLTF-positive cells with strong cytosolic staining as found in the present study (data not shown), suggesting other explanations than processing artefacts." (PMID 16762066, 2006). "Additionally, we examined HLTF expression in GBM tissues and adjacent non‐tumour tissues using qRT‐PCR and immunohistochemistry." (PMID 40000422, 2025). "HLTF are also known to silence genes through promoter hypermethylation or alternative mRNA splicing in various tumours, leading to the truncation of proteins lacking DNA repair domains." (PMID 40000422, 2025). "Because the effects of HLTF-deletion from tumor cells and cells of the TME has never been studied in vivo, we developed a HCT116 cell line-derived xenograft model (CDX) of tumorigenesis." (PMID 37682902, 2023). "RNAseq with species-specific mapping unambiguously differentiated gene expression in tumor cells from cells of the TME and showed Hltf-deletion from the mouse TME reprogramed the HLTF+/+ human tumor transcriptome and initiated a gene deletion-specific program for metastasis." (PMID 37682902, 2023). "Finally, four potential tumor antigens were identified, each related to prognosis and antigen-presenting cell infiltration in STS: HLTF, ITGA10, PLCG1, and TTC3." (PMID 35053609, 2022). "Also, methylation of HLTF and HPP1 genes was detected more frequently in metastatic CRC patients and in patients with high tumor stage." (PMID 33693004, 2021).
tumor (continued). "In contrast, immunohistochemistry showed negligible HLTF protein in fibroblasts of the tumor microenvironment (TME) regardless of tumor stage." (PMID 34010296, 2021). "Also, the expression of both genes in tissue samples showed a reduction of expression in tumor samples compared to normal samples and the reduction of expression in SEPT9 gene was more than that of HLTF gene in tissue samples, like blood samples." (PMID 33936232, 2021). "Given that elevated LDH indicates cell membrane damage, this observation might be a hint that methylated HLTF and HPP1 DNA is released by tumor cells undergoing cell death." (PMID 24708595, 2014). "Intriguingly, HLTF over-expression was never detected in differential gene expression profiles performed between tumor tissue and its normal counterpart." (PMID 16762066, 2006). "Moreover, if all cells were HLTF positive in HKT-1097 cells cultured in vitro, the same decrease in HLTF signal was observed in tumours derived from these cells in nude mice." (PMID 16762066, 2006). "There is a negative correlation between HLTF expression in tumor cells and survival in mice." (PMID 34010296, 2021). "Tumor cell populations could be HLTF positive and S100 negative, HLTF negative and S100 positive or could exhibit both markers." (PMID 16762066, 2006). "If a similar pattern occurred in tumors derived from other tissues, the 10–20 fold increase in HLTF expression in 10% of tumor cells would be diluted out in the population of HLTF negative cells, and it might not be detected upon analyses of whole tumor homogenates." (PMID 16762066, 2006). "Accumulating evidences showed that HLTF (helicase-like transcription factor) and SHPRH, the representative members of SHPRH subfamily, are effective tumor suppressors with non-reductant functions." (PMID 36987072, 2023).